BCL2 (BCL2 apoptosis regulator)
Diseases named in the same sentence as BCL2 in open-access papers (continued):
Sharing a sentence is not in itself a finding about the gene and the disease.
cancer (continued). "Our study demonstrates that ZEB2 induces survival and subsequent seeding of CTCs, maybe through direct upregulation of pro-survival factors such as survivin and bcl-2, and thus probably contributes to cancer cell dissemination in vivo." (PMID 29416649, 2018). "To answer these questions, we developed a screening strategy to assess the sensitivity of cancer cell lines to all possible combinations of a selective BCL-2 inhibitor (ABT-199), a selective BCL-XL inhibitor (WEHI-539), and a selective MCL-1 inhibitor (A-1210477)." (PMID 30158527, 2018). "Stat 3 has oncogenic potential and regulates many aspects of cancer progression, including promoting cell proliferation, promoting cell cycle progression, and inhibiting apoptosis through the induction of genes such as Bcl-2." (PMID 35541462, 2018). "EGCG has been found to affect several cancer-related proteins including Cyclin-dependent kinase inhibitor p27 (p27), Bcl-2 or Bcr-Abl oncoproteins, Bax, matrix metalloproteinases (MMP-2 and MMP-9) the androgen receptor, EGF receptor, Activator proteins 1(AP1), and some cell cycle regulators." (PMID 30701033, 2018). "Interestingly, the BCL-2-related apoptosis pathway and cyclin D1-related pathway were reported to be the targets of miR-34c in cancer." (PMID 29654165, 2018). "It has been proposed that BAG3 is a co-chaperone of HSP70 induced by the HSF-1 transcription factor, and that it critically regulates Bcl-2 and Mcl-1 levels by inhibiting the proteasomal degradation of anti-apoptotic proteins, increasing the resistance of cancer cells to various therapies." (PMID 30486451, 2018). "As interactions between BH3-only proteins and anti-apoptotic members of the BCL-2 family occur in a selective manner, elimination of cancer cells may require the blockage of all or some anti-apoptotic BCL-2 proteins at the same time to induce death." (PMID 29747654, 2018). "Thus, combining the two treatments to inhibit MCL‐1 together with BCL‐2/BCL‐XL should effectively induce apoptosis in cancer cells." (PMID 29352505, 2018). "Future studies that characterize the specific pathways mediating synthetic lethality following PPI and Bcl-2 inhibitors may provide additional strategies to enhance cancer cell death." (PMID 29789637, 2018). "In addition, gossypol prevents the interaction between Bcl-2 and Beclin-1 at the endoplasmic reticulum, decreases the levels of Bcl-2 and increases Beclin-1 expression by inducing Beclin-1 Atg5-a dependent autophagic pathway in cancer cells." (PMID 30459622, 2018). "However, although CLL is an example of a disease quite homogeneously dependent on BCL-2, a cancer homogeneously dependent on MCL-1 has yet to be identified." (PMID 29077093, 2018). "In addition, the expression level of key proteins found to be over-expressed frequently existed in cancer stem cells, and anti-apoptotic protein Bcl-2, Notch-1 and MMP-9 were detected to increase in different degrees." (PMID 29914196, 2018). "Here we develop a drug screening approach to define the sensitivity of cancer cells from ten tissue types to all possible combinations of selective BCL-2, BCL-XL, and MCL-1 inhibitors and discover that most cell lines depend on at least one combination for survival." (PMID 30158527, 2018). "In the present work, according to our previous studies in this cancer cell, also pro-apoptotic protein Bax was activated by the treatment with the three essential oils in DU-145 cells, shifting the Bax/Bcl-2 ratio in favor of apoptosis." (PMID 29351194, 2018). "This study suggests that cancers with functional Bcl-2 expression may be selectively re-sensitised to drugs by Ad∆∆." (PMID 29362360, 2018).
cancer (continued). "Thus, it appears that even transient knockdown of UNC5A leads to robust/permanent activation of BCL2, which is similar to previously reported stable activation of cancer germline genes upon transient knockdown of DNA methyltransferase 1 (DNMT1)." (PMID 29720215, 2018). "Importantly, the long-chain alkyl group in the antimycin-type depsipeptide scaffold is reportedly essential for the Bcl2/Bcl-xL inhibitory activity, which leads to cancer cell death." (PMID 30166552, 2018). "We found that expression of anti-apoptotic Bcl-2 was increased in the H460 resistant cancer cells, which may contribute towards paclitaxel resistance." (PMID 29899843, 2018). "This indicates Bcl-2 functional conversion methods could be combined with existing chemotherapeutics to enhance therapeutic efficacy and sensitize resistant cancer cells to paclitaxel." (PMID 29899843, 2018). "Moreover, Bcl-2 inhibition and Bax activation are thought to be promising approaches for cancer therapy." (PMID 30103745, 2018). "Furthermore, the augmentation of Bcl-2 and diminution of Bax also manipulate anoikis in cancer cells." (PMID 29631569, 2018). "Overexpression of BCL2 lets cancer cells evade apoptosis, the process of programmed cell death." (PMID 29298978, 2018). "However, ABT-199 shows limited efficacy in most cancers due to the functional redundancy of Bcl-2, Bcl-xL, and Mcl-1 in anti-apoptosis." (PMID 29520102, 2018). "Similarly, PPARα serves as E3 ligase to induce Bcl2 ubiquitination and degradation leading to increased cancer cell apoptosis in response to chemotherapeutic agents." (PMID 30519260, 2018). "Hence, targeting the interactions of VDAC1 with anti‐apoptotic proteins (Bcl‐2, Bcl‐xL) or proteins supporting the metabolic requirements of cancer cells (HK‐I, HK‐II) is a promising strategy for the development of anticancer agents." (PMID 29698587, 2018). "In CLL and other cancers, anti-apoptotic BCL2 has been identified as a target of miR-15a." (PMID 29416778, 2018). "Moreover, it has been reported that wogonin-induced apoptosis was also accompanied by a significant decrease of survivin along with Bcl-2 and increase of Bax in cancer cells." (PMID 29670184, 2018). "Transcripts of Versican, Vegf-c, Bcl-2, Mmp-9, Il-6 and KC were up-modulated in pituitaries isolated from transgenic mice; in in vitro studies, exogenous hCG has been shown to up-modulate transcription and expression of these molecules in cancer cells." (PMID 30410667, 2018). "It was demonstrated that overexpression of Bcl-2 may protect the cancer cell from cell death while decrease in expression may trigger apoptosis." (PMID 29890640, 2018). "Previous study reported that overexpression BCL2 can inhibit apoptosis in cancer cells." (PMID 30400936, 2018). "Additionally, the co-regulation of Bcl-2 and c-myc was also found to be related to cell proliferation and apoptosis in malignant tumors." (PMID 30429828, 2018). "This upregulation can occur through a variety of mechanisms including chromosomal translocation, gene amplification, increased gene expression/translation or protein stability with various mechanisms and alternative pro-survival BCL-2 protein increases seeming more prominent in particular cancers." (PMID 29769323, 2018). "As Bcl-2 upregulation has been implicated in resistance mechanisms to other therapeutic agents, such as cisplatin, in multiple cancer types, there is great potential to use NuBCP-9 enabled Bcl-2 functional conversion to treat an array of therapy resistant cancers." (PMID 29899843, 2018).
cancer (continued). "In addition, expression of Bcl-2 was very low in normal fibroblast and non-cancer HaCaT cells, comparing to HCT116, provided the clue why these cells were resistant to IPP-14 induced p21." (PMID 28423593, 2017). "In sum, we demonstrated for the first time that the compound C2.01 inhibits specific La:RNA interactions in cells and sensitizes cancer cells for cisplatin treatment, likley by reducing the binding of La to Bcl2 mRNA, leading to reduced expression of anti-apoptotic factor Bcl2." (PMID 28291789, 2017). "The ability of F. umbellata MeOH extract to decrease the anti-apoptotic Bcl-xL and Bcl-2 proteins expression might inhibit the capacity of cancer cells to ignore apoptosis signal." (PMID 28545243, 2017). "In addition, overexpression of TFF3 decreased the sensitivity of cancer cells to chemotherapy by mediating Bcl-2." (PMID 28070169, 2017). "In the present study, Bcl2 protein was expressed in all cancer tissues." (PMID 29104726, 2017). "Similarly, the angiogenesis-mediated protein (VEGFA) and the antiapoptotic marker (Bcl2) were expressed in all cancer tissues." (PMID 29104726, 2017). "The expression of Bcl-2 at both the transcription and protein levels in vitro and in vivo was efficiently inhibited by the CNCs; this inhibition effect increased the sensitivity of the cancer cells to DTX and subsequently induced enhanced apoptosis." (PMID 28383524, 2017). "In addition oncogenic expression of Bcl-2 protein plays crucial role in survival mechanism of cancer cells." (PMID 28611451, 2017). "Inactivation of BCL2 is known to induce apoptosis and protects from cancer progression." (PMID 28835693, 2017). "Cancer cells express series of anti-apoptotic proteins such as Bcl2 and BclxL." (PMID 28049506, 2017). "Hence, BH3-mimetics alleviate the inhibition of Bax and Bak by the anti-apoptotic Bcl-2-family members, effectively killing cancer cells that are dependent on anti-apoptotic Bcl-2 proteins for their survival." (PMID 28516063, 2017). "The ratio of Bcl-2/Bax takes on a higher level in cancer cells compared with the original cells." (PMID 28701952, 2017). "Thus, the genetic background of a cell determines which pathway is triggered, a death signals to regulate autophagy initiation between beclin-1/Bcl-2 interaction, and this provides new insight into cancer control and therapy." (PMID 29212215, 2017). "Hence, these data support the concept of the dual dependence of cancer cells on Bcl-2 for their survival with respect to the oncogenic signaling either by Bim upregulation or by IP3R2 upregulation." (PMID 29340082, 2017). "In addition, increased levels of Bcl-2 or Mcl-1 promote accumulation of apoptotic resistant neoplastic cells and also help cancer cells evade immune-surveillance." (PMID 29156771, 2017). "Take together, the results suggested that the target compound could act as a potential apoptosis inducer mediated-mitochondria through binding to the bcl-2 G-quadruplex DNA in cancer chemotherapy." (PMID 28531122, 2017). "The results indicated that multiple genes and transcriptional factors related to cancer apoptosis and progression, such as Bak1, Bcl-2, KLF13 and STAT3, might be the target genes of miR-125b." (PMID 28176874, 2017).
cancer (continued). "Indeed, cancer cells are addicted to Bcl-2 for their survival due to their continuous and permanent ongoing apoptotic signaling." (PMID 29340082, 2017). "Furthermore, successful transfection of EpCAM overexpression in cancer cells led to upregulation of Bcl-2 expression and downregulation of concomitant Bax expression." (PMID 28574829, 2017). "Thus, IPP-14 would be one of plausible anti-cancer drug candidate against PAK1 activated or Bcl-2 overexpressed cancers." (PMID 28423593, 2017). "Akt could phosphorylate Bad and dissociate Bad with Bcl-2, which suppresses the activity of Bax and leads to the avoidance of apoptosis in cancer cells." (PMID 28056952, 2017). "Thus, cancer cells can exploit both of the anti-apoptotic actions of Bcl-2 to promote their survival, dependent on the challenging conditions operative in these cells, either by Bim upregulation or by IP3R2 upregulation." (PMID 29340082, 2017). "Subsequently, Bcl-2 expression level was significantly decreased in both NPs-treated cancer cells by more than 15 folds and 5 folds compared to untreated healthy cancer cells and 5-FU-treated cancer cells, respectively." (PMID 29196676, 2017). "In summary, our study raised a novel mechanism for developing of EMT in the presence of Bcl-2 and cancer progression mediated by a Bcl-2/Twist1 functional complex, which may provide a new therapeutic target for OSCC treatment." (PMID 28032603, 2017). "MiR-139-5p has been reported to promoting apoptosis by targeting c-Met and BCL2 in cancer cells." (PMID 28346520, 2017). "As metabolic organs are directly exposed to high levels of glucose and other nutrients, we predicted that hyperacetylated and inactivated ECHS1 accumulated BCAAs and FAs; therefore, increased BCL-2 expression would be observed in cancers originating from these organs." (PMID 28878358, 2017). "At the same time, cancer cells may overexpress the anti-apoptotic Bcl-2 proteins thus modulating the intrinsic pathways as well." (PMID 29089545, 2017). "Therefore, the process of regulating Bcl-2 stability seems to be crucial in sensitizing cancer cells to chemotherapeutics." (PMID 28537875, 2017). "As same as Bcl2 and c-Met, these genes also play crucial roles in the development of cancer." (PMID 28615991, 2017). "Additionally, EGCG is also capable of inducing cancer stem cells to apoptosis by restraining the expression of Bcl-2, followed by activating Caspase-9 and its downstream Caspase-3." (PMID 28969057, 2017). "Highly primed cancers may be sensitive to the knockdown of any individual anti-apoptotic BCL-2 member even though they predominantly express one anti-apoptotic BCL-2 member." (PMID 28714472, 2017). "The appropriate balance of interactions between pro-survival and pro-death Bcl-2 family members in healthy cells is often disrupted in cancer cells, where overexpression of anti-apoptotic Bcl-2 proteins can promote oncogenesis and confer resistance to chemotherapeutic agents." (PMID 28594323, 2017). "In cancer, overexpression of the antiapoptotic Bcl2 can result in a distinct cellular growth advantage due to lack of cell death, a hallmark of cancer." (PMID 29104726, 2017). "Bcl-2 is often upregulated in cancers to neutralize the BH3-only protein Bim at the mitochondria." (PMID 29340082, 2017). "Importantly, the chemotherapeutic response of cancer cells appears to correlate with the mitochondrial “primed to death” status of Bcl-2 and thus their sensitivity to BH3 mimetics." (PMID 29340082, 2017). "Up-regulation of Bax and down-regulation of Bcl-2 could facilitate apoptosis in various cancer cells of different origins." (PMID 28701952, 2017). "Bax/Bcl‐2 ratio is considered as a good marker of the running apoptosis in cancer model studies." (PMID 28524540, 2017).
cancer (continued). "PUMA induction potently promotes apoptosis in cancer cells by binding to antiapoptotic Bcl-2 family members (Bcl-2 and Bcl-XL), which activates the proapoptotic Bcl-2 family members (Bax and Bak), resulting in dysfunction of mitochondrial leading to caspase cascade activity." (PMID 29137323, 2017). "Res and PA combination had a strong expression increasing effect of Bax and decreasing effects of Bcl-2, Bcl-xL, Res and PA might raise anticancer effects in HepG2 cancer cells by these mechanisms." (PMID 28978315, 2017). "miR‐15b transfection into cancer cells has been shown to lead to decreased expression of Bcl‐2, cyclin E and PIM1 proteins, providing additional mechanistic explanations of how miR‐15b might play an important role in the development drug resistance." (PMID 28145098, 2017). "The apoptotic pathway assessments with Western blot assays confirmed that CeO2-NCs targeted to HT29 cancer cell lines altered the expression levels of the anti-apoptotic proteins Bcl2 and BclxL, and increased the expression of the Bax, PARP, and cytochrome c proteins." (PMID 28634498, 2017). "The role of Bcl-2 may be intriguing in this context: cancer cells are often dysregulated in the apoptotic response but the persistently low Bcl-2/Bax ratio might even promote the pro-apoptotic effect of phytochemicals." (PMID 28098843, 2017). "Bcl-2 was initially recognized as an oncogene in follicular lymphoma; however, some recent reports suggest contradictory effects of this protein in different cancer entities." (PMID 28662697, 2017). "In a word, this kind of compound may develop as a potential apoptosis inducer in cancer chemotherapy via binding and stabilizing to the bcl-2 G-quadruplex DNA." (PMID 28531122, 2017). "In addition, it is well known that PCNA/KI67 and Caspase-3/Bcl-2 are important molecular pathways in cancer cell proliferation and apoptosis." (PMID 28032589, 2017). "It is more interesting that MYC and BCL2 may act synergistically to promote the generation of cancer cells." (PMID 28615526, 2017). "A growing body of cancer research evidence has indicated that activation of gp130/STAT3 induces the expression of multiple survival, proliferation and antiapoptosis associated genes, such as MCL-1, Bcl-2, Bcl-XL, Survivin and cyclin D1." (PMID 27537522, 2016). "Furthermore, it was also observed that IL-11 induced STAT3 phosphorylation and increased anti-apoptotic protein Bcl-2 and Survivin expression in cancer cells." (PMID 27922075, 2016). "Some miRs have been shown to confer drug resistance in various human cancers via targeting Bcl-2." (PMID 27083050, 2016). "Previous studies show that NR4A1 acts as a coactivator of genes with GC-rich promoters (pathway 3) that play a role in cancer cell proliferation and survival, and these include survivin, bcl-2, cyclin D1, epidermal growth factor receptor (EGFR) and the oncogene cMyc." (PMID 27144436, 2016). "Therefore, the synthesized 1b has impressive bcl-2 G-quadruplex DNA-binding and stabilizing activities with potential applications in cancer chemotherapy." (PMID 28773504, 2016).